IKZF1 (IKAROS family zinc finger 1)
Diseases named in the same sentence as IKZF1 in open-access papers (continued):
Sharing a sentence is not in itself a finding about the gene and the disease.
tumor (continued). "The IKZF1 gene encodes IKAROS, which acts as a tumor suppressor in B-ALL." (PMID 33531656, 2021). "In our study, upregulation of LINC00324, GAB3 as well as IKZF1 in TAM low-risk group could predict a better prognosis, suggesting the potential anti-tumor immunology role in the TME." (PMID 33738286, 2021). "IKZF1 is a tumor suppressor gene and a transcription factor regulator of lymphocyte." (PMID 33369444, 2020). "The results suggested that IKZF1 is expressed in both tumor cells and lymphocytes." (PMID 31320627, 2019). "IKZF1 has not been associated with cardiac development and is better known for its role in haematopoietic differentiation, tumour suppression and chromatin regulation." (PMID 27683156, 2016). "Additionally, to estimate immune cell prevalence we used the average expression of the lymphocyte-specific genes GZMB, PRF1, CXCL13, IRF1, IKZF1, and HLA-E in each tumor sample." (PMID 27959926, 2016). "BCAT1 and IKZF1 are both involved in tumour growth and invasiveness." (PMID 25928810, 2015). "Notably, Ikzf1 is a haplo-insufficient tumour suppressor that has been reported to act as a transcriptional suppressor of Myc, while intragenic retroviral insertions lead to expression of truncated isoforms with dominant negative potential." (PMID 24586197, 2014). "Consequently, IKZF1 deletions may be difficult to detect in samples with low tumor cell content or leukemic subclones by conventional techniques." (PMID 37469802, 2023). "Moreover, among different tumor locations, Ikaros genes were expressed at the highest levels in regional lymph nodes, IKZF1 and IKZF3 were expressed at the lowest levels in distant metastases, and IKZF2, IKZF4, and IKZF5 were expressed at the lowest levels in the primary tumor." (PMID 36353107, 2022). "This may also explain the lack of significant tumor PAI for the IKZF1 SNP rs4132601, as hemizygous IKZF1 loss has such a strong leukemogenic effect that there is less selective pressure on the remaining allele." (PMID 26575185, 2015). "Despite longstanding recognition of IKZF1 as a tumor suppressor in B-ALL, the molecular mechanisms by which IKAROS enforces lineage restriction and constrains leukemic programs in humans have remained incompletely defined." (PMID 41509392, 2025). "The most downregulated genes contained known tumor suppressors (ZNF831, AKNA, NR4A1, ARHGAP9, ZBTB16) and regulators of immune response (NLRC5, WDFY4, RASGRP2, IKZF1)." (PMID 39794830, 2025). "Usually, when analyzing the tumor genome by CMA, aberrations larger than 5 MB and additional microdeletions involving the CDKN2A/B, BTG1, EBF1, ETV6, ERG, IKZF1, PAX5, and RB1 genes are taken into account." (PMID 39408811, 2024). "IKZF1/3 control IRF4 expression and its downstream effector c-Myc are the main drivers for tumor cell growth in MM." (PMID 38344143, 2023). "To determine the role of Ikzf1 in the Tpex to Tex cell transition, we sorted Tpex cells targeted with sgNTC or sgIkzf1 from B16-OVA tumours and transferred them to new tumour-bearing mice." (PMID 37968405, 2023). "The anti-tumor effects induced by LEN are mediated through the modification of the target specificity of CRBN, an E3 enzyme responsible for ubiquitinating IKZF1 and IKZF3 in MM cells, as well as casein kinase 1 alpha (CK1α) in 5q-MDS." (PMID 38344143, 2023).
tumor (continued). "Tumor infiltration analysis using CIBESORT and Estimate, shows that the stromal and immune scores significantly increased as the expression of IKZF1–3 was enhanced in SKCM samples." (PMID 36353107, 2022). "As expected, the master regulator IKZF1 overexpression led to enhanced immune infiltrate recruitment and tumor sensitivity to PD-1 and CTLA-4 inhibitors in cancers that typically lack IKZF1 expression." (PMID 33291616, 2020). "In BC, IL-7 promotes tumor growth by activating the JAK1/3-STAT5 and PI3K/AKT pathways, while the IKZF1 gene plays important regulatory roles in lymphogenesis." (PMID 33164640, 2020). "The significant genes observed were PYHIN1, IKZF1, CASP8, DAPK1 and SMCHD1 expression in tumor samples." (PMID 30867653, 2019). "Deregulation of IKZF1 and BCAT1 is involved in tumour growth and invasiveness in several cancers, including CRC." (PMID 29796114, 2018). "Most tumour tissues displayed elevated methylation of both BCAT1 and IKZF1 (n = 78, 85.7%), while ctDNA methylated in both genes was only detected in 30 patients (33.0%)." (PMID 29796114, 2018). "IKZF1 and IKZF3 are considered tumor suppressors and their inability to perform their functions are connected with tumor development." (PMID 29903986, 2018). "The top TFs found to negatively regulate the expression of cell cycle genes (SMAD5, IKZF1, USF1, USF2) have been previously shown to have a role as transcriptional repressors and as inhibitors of cellular proliferation in tumor cell lines." (PMID 28899340, 2017). "The CK2 inhibitor, TBB, which restores IKZF1 tumor suppressor activity, increased the suppression of CRLF2 expression and IKZF1 knockdown blocks the TBB-induced changes." (PMID 27391346, 2016). "Binding of the drug to cereblon leads to degradation of Ikaros family zinc finger proteins IKZF1 and IKZF3, which then leads to inhibition of tumor cell growth and immune activation." (PMID 28018601, 2016). "To validate SMART-ddPCR measurements of AI using a second method, we carried out Sanger sequencing across the IKZF1 and ARID5B SNPs for constitutional and tumor DNA from SNP heterozygotes." (PMID 26575185, 2015). "Similarly, the IKZF1 SNP rs4132601 showed a non-significant trend towards preferential retention of the risk allele and loss of the protective allele in the tumor, for which we would have required almost 4-fold the number of samples (61 vs. 43) to reveal significant PAI." (PMID 26575185, 2015). "Tumor bulk RNA-Seq data highlighted that the tumor expression of 5/32 genes (IRF1, IKZF1, SPI1, SH2B3, LAT) was each strongly correlated (Spearman’s ρ > 0.5) with at least one intra-tumor T/myeloid cell infiltration marker (CD4, CD8A, CD11B, CD45) in every one of the cancer types." (PMID 40428397, 2025). "Indeed, the WGCNA of TCGA-LUAD cohort revealed that patients with this tumor phenotype had down-regulated an extensive gene network led by SASH3 and including IKZF1, IL10RA, CD53 and SNX20, all involved in immune activation." (PMID 39107857, 2024). "Identification of such patients by means of assaying for circulating DNA methylated in BCAT1/IKZF1 does not require genomic analysis of the tumor tissue." (PMID 35822405, 2023). "Here, we demonstrated that detection of circulating methylated BCAT1/IKZF1 DNA is indicative of the presence of tumor even if it is not radiographic apparent." (PMID 35822405, 2023). "Hence, a possible tumor suppressive mechanism of Ikaros is to activate the expression of a miRNA (hsa-miR-663a) that represses ABL1 expression to restrict cell growth, and mutation in IKZF1 in Ph+ B-ALL could relieve such oncogene repression by reduced tsmiR levels." (PMID 36278683, 2022). "RNA‐NGS and CGAT are complementary in detecting IKZF1 deletion, such that RNA‐NGS is more sensitive in detecting deletions that lead to oncogenic isoforms, namely IKZF1 Δ4‐7, while CGAT had missed several cases in our study with relatively low tumor content." (PMID 34288525, 2021).
tumor (continued). "Abundance of Ikzf1 and Pax5 transcription factor mRNA was not significantly different in tumor vs unaffected cells, but was markedly lower than in pre-B cells from wild-type and Bcl-xLTg mice." (PMID 28692033, 2017). "Therefore, the selective pressure during the initial hyperdiploid event would be less than that for SNPs within regions of secondary tumor alterations, such as deletions of CDKN2A and IKZF1." (PMID 26575185, 2015). "Within CK2 targets, an important role is played by the transcription factor IKZF1 that acts as a tumor suppressor in T- and B-ALL; genome-wide analyses have shown that 30% of pediatric B-ALL and approximately 5% of T-ALL present a deletion or dysfunction of the IKZF1 gene." (PMID 39940843, 2025). "Moreover, lenalidomide, an IKZF1/3 degrader, combined with R‐CHOP, improves the poor prognosis of A7 DLBCL patients by boosting T‐cell trafficking and MHC expression, promoting CD8+ T‐cell recognition of tumor cells." (PMID 41190308, 2025). "However, the associations of the OS, DSS, and PFI rates of patients with higher expression levels of IKZF4–5 were not significantly different, and patients who expressed high levels of IKZF1–3 experienced significantly longer DSS and longer tumor progression-free survival." (PMID 36353107, 2022). "Thus, the mechanisms of the IKZF1 role in CRC prognosis could be complicated and may involve tumor cells as well as infiltrating lymphocytes." (PMID 31320627, 2019). "Interestingly, we found super-enhancers near not only oncogenes but also tumor suppressor genes (IKZF1, LEF1, RUNX1), implying that not all super-enhancer associated genes contribute to tumor progression." (PMID 30304769, 2018). "This drastic decrease in mRNA levels of IKZF1 in the tumours may not imply a signature change in HCC, but a potential role of this change in the elevation of MDIG mRNA." (PMID 28471446, 2017). "Remarkably, expression levels of key AST factors, IKZF1, NFE2, and IRF8, were significantly enriched in CTCs that were, however, largely absent in primary tumor cells." (PMID 36991428, 2023). "The disappearance of circulating methylated BCAT1 and IKZF1 DNA after tumour resection in 10 of 12 cancer cases shows that detection of methylated BCAT1 and IKZF1 DNA in the blood reflects the presence of CRC rather than a risk of developing CRC." (PMID 26445409, 2015). "Hence, tumor genotyping is not required if these two methylation biomarkers are used for ctDNA detection, and testing for methylated BCAT1/IKZF1 ctDNA is unlikely to be confounded by tumor heterogeneity or clonal drift following adjuvant therapy." (PMID 35822405, 2023). "Therefore, it is possible that IKZF1 could work as a negative transcriptional regulator of the RAS pathway by binding to the PTPN11 promoter and directly suppressing its activity, and thus tumor cells may not need both altered pathways to drive disease relapse." (PMID 39766099, 2024).
cancer (71 papers, 2013 to 2025). A tumor composed of atypical neoplastic, often pleomorphic cells that invade other tissues. "For rs10230978 and rs3184504, the allele that increased cancer risk decreased the expression of IKZF1 and SH2B3, respectively." (PMID 40428397, 2025). "Intriguingly, IKZF1 was demonstrated to enhance immune infiltrate recruitment in several cancer types including LUAD, and thus susceptibility to immunotherapy." (PMID 36304306, 2022). "IKZF1 mutation has been identified in the activation of several recurrent genes that help in the metastasis of cancer cells in a hypoxic environment, which can be detected in both myeloid and lymphoid BC." (PMID 35847841, 2022). "It indeed has been proven that several of the genes known to be somatically mutated in cancer types (i.e., IKZF1 in leukemia), are found to be germline mutated through i.e., familial cancer studies, and thus getting recognized as cancer predisposition genes." (PMID 30443258, 2018). "For a specimen containing approximately 5 % methylated BCAT1 and IKZF1 DNA the models estimate a relative risk of 5 for having early stage cancer." (PMID 26445409, 2015). "Besides, the hypomethylated pattern of CpG island in the IKZF1 promoter region may be the basis of abnormal Ikaros expression patterns associated with malignant tumors." (PMID 34950704, 2021). "Exemplary cases include ncORFs in the cancer hallmark genes CREBBP, CRTC1, CSF3R, FGFR2, IKZF1 and MAP2K2 with peptide support in all but two of the analyzed cancer types." (PMID 37275273, 2023). "MYC, a multifunctional transcription factor protein, behaved as a common gene signature upregulated by IKZF1 N159Y/S,25, 34 and contributed to the pathogenesis of various types of human cancers through different mechanisms." (PMID 37345307, 2023). "We found that most patients with cancer that highly expressed IKZF1–3 had a significantly improved prognosis." (PMID 36353107, 2022). "We employed different analytical methods to identify the relationship between the transcriptional properties of IKZF1–5 and different cancers." (PMID 36353107, 2022). "Sequencing DNAs from MD tumors and their matching controls, somatic mutations were repeatedly identified in key domains of Ikaros (IKZF1) that are also known to exist in several human cancers." (PMID 35208856, 2022). "Using the upper IQR values measured in non-neoplastic tissues as positivity thresholds, hypermethylation of BCAT1 and IKZF1 was observed in 82/91 (90.1%) and 75/91 (82.4%) of cancers, respectively, with 86/91 (94.5%) having elevated levels for either marker." (PMID 29796114, 2018). "This study has shown that BCAT1 and IKZF1 methylation are common events in CRC with almost all cancer tissues showing significant levels of methylation in the two genes." (PMID 29796114, 2018). "Both the frequency of detection and the amount of methylated BCAT1 and/or IKZF1 DNA released into blood increased with cancer stage." (PMID 25928810, 2015). "We determined that less than 8% of positive control plasma specimens are found to contain at least 20 pg of methylated BCAT1 or IKZF1 DNA, while 63–77% of early stage cancers had 20 pg or more." (PMID 25928810, 2015). "Methylated BCAT1 and IKZF1 DNA were detected in respectively 48 (65%) and 50 (68%) of the 74 cancers." (PMID 25928810, 2015). "In addition, we detected variants in several known cancer predisposition genes (eg, ETV6, RUNX1, ANKRD26, and IKZF1), highlighting the importance of long-term surveillance and genetic counseling in IPDs with potential malignant transformation risk." (PMID 40488176, 2025).
cancer (continued). "Biological variables associated to a high risk of progression included CIP2A levels, the expression levels of the polycomb group BMI1 gene, the activation of beta-catenin, specific gene signatures, and mutations in cancer-associated genes such as ASXL1, IKZF1, RUNX1, SETD1B, GATA2, MLL, and UBE2A." (PMID 31709190, 2019). "However, there was no thorough paper about ITGB2-AS1, except that ITGB2-AS1 was reported to have high co-expression with multiple cancer genes (IKZF1, LCK, and WAS)." (PMID 29941860, 2018). "In addition, IKZF1 encodes a TF regulating lymphocyte differentiation, and INHBA, which belongs to the TGF-β superfamily, is associated with several cancers." (PMID 27829444, 2016). "Data for BCAT1 and IKZF1 cancer and normal subjects have been published elsewhere." (PMID 27983717, 2016). "Thus the likelihood of a plasma specimen with ≥ 20 pg methylated BCAT1 or IKZF1 DNA to be an early stage cancer is approximately 9:1 and 210:1, respectively (early stage CRC: control)." (PMID 25928810, 2015). "A comparison of this list with known human cancer driver genes revealed Cdk6 and Ikzf1 (Ikaros) as two genes whose amplifications may drive tumorigenesis." (PMID 25452272, 2014). "CDKN2A, IKZF1, ETV6, RUNX1, and FLT3 were the top genes mutated in leukemias, while somatic alterations in ALK, NF1, and PTEN primarily occurred in solid tumors, suggesting that the driver alterations are either common to cancer (e.g., cell cycle) or specific to pediatric cancer histotype." (PMID 36845394, 2023). "Taken together, these experiments indicate that all 6 compounds have anti-proliferative activity in IKZF1-dependent and independent cell lines in a concentration-dependent manner, indicating that other substrates are degraded by these compounds that account for the toxicity in cancer cells." (PMID 38114468, 2023). "Therefore, the reduction of IKZF1 protein may function as a double-edged sword in the pathogenesis of cancers." (PMID 35414773, 2022). "Furthermore, the transcriptional signatures of individual Ikaros genes in different cancer types revealed that IKZF1–5 were mainly overexpressed in hematological tumors such as LAML and DLBC, but were expressed at low levels in digestive tumors, for example, LIHC." (PMID 36353107, 2022). "By identifying the synthetic lethal partner of GSPT1, researchers hope to identify more sensitive indications for targeting GSPT1, including MYC, IKZF1/3, BTK, AR/ARv7, and mTOR‐driven cancers." (PMID 41194439, 2025). "Here, we describe screening of a library of cereblon (CRBN) ligands against a panel of patient-derived cancer cell lines, leading to the discovery of SJ7095, a potent degrader of CK1α, IKZF1 and IKZF3 proteins." (PMID 38228616, 2024). "This revealed E14 as a potent MG degrader targeting IKZF1/3, GSPT1 and 2 with profound effects on a panel of cancer cells." (PMID 38114468, 2023). "Several have been proposed for the detection of PDAC or other cancers in blood, including BCAN, IKZF1, TBX15, BNC1 and SHOX2." (PMID 36434648, 2022). "These obtained opto-PROTACs were able to degrade IKZF1/3, BRDs or ALK fusion protein (using corresponding POI ligands) upon 365 nm UV irradiation, inhibiting cancer cell proliferation in an optical-controlled manner." (PMID 35410300, 2022). "The results confirmed the transcriptional relationship between IKZF1 and IKZF3, because they ranked in the same cluster with a transcriptional pattern similar to that of IKZF1 and IKZF3 in different cancer types." (PMID 36353107, 2022). "As well-described for c-MYC, both IKZF1 and IRF4 are involved in the development of cancer, including CRC." (PMID 33478584, 2021).